ZCCHC7 (zinc finger CCHC-type containing 7)
Synonyms: HSPC086; FLJ22611; AIR1
Tractability: PROTAC: UniProt records ubiquitination sites on it; ubiquitination databases record sites on it.
Gene: Protein-coding gene on chromosome 9 (37,120,478 to 37,358,177, forward strand). Ensembl gene ENSG00000147905.
Subcellular location: Nucleus, nucleolus
Subcellular location (Human Protein Atlas): Cytosol; Nucleoli
Pathways (Reactome):
Metabolism of RNA: Nuclear RNA decay
Gene Ontology:
Molecular function: protein binding; RNA binding; nucleic acid binding; zinc ion binding
Biological process: nuclear mRNA surveillance of mRNA 3'-end processing; nuclear polyadenylation-dependent CUT catabolic process; nuclear polyadenylation-dependent rRNA catabolic process; nuclear polyadenylation-dependent snoRNA catabolic process; nuclear polyadenylation-dependent snRNA catabolic process; TRAMP-dependent tRNA surveillance pathway
Cellular component: cytosol; nucleolus; nucleus; TRAMP complex
Genetic constraint (gnomAD): Loss-of-function variants: 40 observed, 50.67 expected, observed/expected ratio (o/e) 0.79, 90% interval 0.61 to 1.03. The upper end of that interval is the gene's LOEUF score, 1.03, which puts it in group 4 of 6, group 1 being the genes least tolerant of losing a copy. Missense variants: 536 observed, 614.69 expected, observed/expected ratio (o/e) 0.87, 90% interval 0.81 to 0.94. Synonymous variants: 201 observed, 212.96 expected, observed/expected ratio (o/e) 0.94, 90% interval 0.84 to 1.06.
Homologues: Orthologues: chimpanzee ZCCHC7 (99% identical), macaque ZCCHC7 (96% identical), rabbit ZCCHC7 (74% identical), dog ZCCHC7 (74% identical), pig ZCCHC7 (73% identical), guinea pig ZCCHC7 (69% identical), mouse Zcchc7 (64% identical), rat Zcchc7 (63% identical), tropical clawed frog zcchc7 (39% identical), zebrafish zcchc7 (33% identical). Paralogues in human: CNBP (9% identical), ZCCHC9 (9% identical), ZCCHC13 (8% identical).
Diseases named in the same sentence as ZCCHC7 in open-access papers:
ZCCHC7 is named in the same sentence as 9 diseases in open-access papers, as found by Europe PMC text mining. Sharing a sentence is not in itself a finding about the gene and the disease. The quoted sentences say what the papers report.
lymphoma (4 papers, 2016 to 2024). A malignant (clonal) proliferation of B- lymphocytes or T- lymphocytes which involves the lymph nodes, bone marrow and/or extranodal sites. "ZCCHC7 encodes a subunit of the Trf4/5-Air1/2-Mtr4 polyadenylation-like complex and demonstrated copy number gain, chromosomal translocation and enhancer retargeting-mediated transcriptional upregulation upon lymphoma transformation." (PMID 38049665, 2023). "In lymphoma cells, the overexpression of ZCCHC7 disrupts the processing of 5.8S rRNA, leading to an accumulation of the precursor 5.8S + 40 rRNA." (PMID 38633862, 2024). "We were therefore interested to learn if pre-rRNA processing and ITS2 maturation, in particular, are altered in lymphoma cells upon ZCCHC7 overexpression." (PMID 38049665, 2023). "Taken together, our results provide evidence of the following three different mechanisms of ZCCHC7 overexpression in DHL: copy number gain, ER and translocation, and a potential role for ZCCHC7 overexpression in lymphoma cell survival." (PMID 38049665, 2023). "An example is the aberrant overexpression of ZCCHC7 in lymphoma cells." (PMID 38633862, 2024). "Finally, they elucidated cellular functions of ZCCHC7 and effects of ZCCHC7 overexpression on lymphoma cells." (PMID 39424289, 2024). "In addition to the processing defects, analysis of nascent peptide synthesis indicates an alteration in protein synthesis under ZCCHC7 overexpression in lymphoma cells." (PMID 38633862, 2024). "Thus, we postulate that increased ZCCHC7 expression in lymphoma cells results in altered kinetics of 5.8S rRNA biogenesis, driving changes in protein synthesis and consequently remodeling of the lymphoma proteome." (PMID 38049665, 2023). "Finally, we reveal the cellular function of ZCCHC7 and the consequences of ZCCHC7 alteration in lymphoma cells." (PMID 38049665, 2023). "Given that both deletion and point mutation of PAX5-TSS2 lead to stronger interactions between the PAX5 enhancer region and the ZCCHC7 promoter and a corresponding increase in ZCCHC7 mRNA expression, we postulate that PAX5 promoter mutations in lymphoma cells increase ZCCHC7 expression." (PMID 38049665, 2023). "Finally, ZCCHC7-related changes to ribosome biogenesis present a mechanism through which the lymphoma proteome changes over time, with important implications for lymphoma biology and clinical management." (PMID 38049665, 2023). "We expect that in addition to the role of ZCCHC7, other mechanisms leading to rRNA processing defects in lymphoma likely will be identified in the future, presenting potential opportunities for the treatment of aggressive lymphomas and/or secondary prevention of lymphoma transformation." (PMID 38049665, 2023). "Notably, this mechanism could explain the ZCCHC7 overexpression that we observe in lymphomas that do not harbor PAX5/ZCCHC7 copy number gains but have PAX5-ZCCHC7 SE mutations." (PMID 38049665, 2023). "ZCCHC7 overexpression via copy number gain or via ER interferes with normal 5.8S rRNA processing in DHL, with the resultant accumulation of 5.8S + 40 pre-rRNA leading to critical rewiring of the lymphoma proteome." (PMID 38049665, 2023). "Additionally, several DLBCL cell lines and primary human DLBCLs harbor PAX5-TSS2 mutations and on average demonstrate increased ZCCHC7 mRNA levels relative to cell lines and tumors without such mutations, suggesting that PAX5 promoter mutations might promote ZCCHC7 overexpression in lymphoma cells." (PMID 38049665, 2023).
acute lymphoblastic leukemia (1 paper, 2021). Leukemia with an acute onset, characterized by the presence of lymphoblasts in the bone marrow and the peripheral blood. "Downregulation of ZCCHC7 was correlated with acute lymphoblastic leukemia (ALL) children at a high risk to relapse, similar to our data that low expression level of ZCCHC7 associated with poor outcome." (PMID 33749163, 2021).
leukemia (1 paper, 2025). A malignant (clonal) hematologic disorder, involving hematopoietic stem cells and characterized by the presence of primitive or atypical myeloid or lymphoid cells in the bone marrow and the blood. "As expected, several previously reported genes with abnormal methylation in leukemias such as CPEB1, BLK, FLT3, ZCCHC7, EBF1, HDACs, IKZF1, RB1, CDK6, DOCK5, DPP10, MUC4, JAKs, KIT, KRAS, LINC01013, MAD1L1, NOTCH1, and STATs, among others, were also detected." (PMID 41226303, 2025).
lung carcinoma (1 paper, 2025). "77, 25, 38 differentially expressed circRNAs were only found in colorectal, stomach, and lung cancer, and ZCCHC7 was the only one such circRNA that was found in HCC." (PMID 40315130, 2025).
tumor (4 papers, 2011 to 2023). "PAX5-ZCCHC7 structural variations are also observed in a subset of B-lymphoblastic leukemia (B-ALL), a neoplasm that demonstrates robust ZCCHC7 expression overall, and especially in treatment-refractory cases, with PAX5-ZCCHC7 positive cases showing the highest levels of ZCCHC7 mRNA expression." (PMID 38049665, 2023).
cancer (1 paper, 2024). A tumor composed of atypical neoplastic, often pleomorphic cells that invade other tissues. "For example, one study documented a non-coding cancer variant that converts an enhancer to target ZCCHC7, leading to protein synthesis rewiring and cancer development." (PMID 39544254, 2024). "Non-coding mutations convert this enhancer to target a different gene (ZCCHC7), which contributes to cancer development by rewiring protein synthesis." (PMID 39544254, 2024).
infection (1 paper, 2015). The state of being infected such as from the introduction of a foreign agent such as serum, vaccine, antigenic substance or organism. "Several infection-induced SUMO targets also are involved in mRNA maturation events, such as 3′ end pre-mRNA processing (CPSF1, CPSF2, FIP1L1, RBBP6, and WDR33), splicing (CLASRP, SFPQ, and ZRANB2), and nuclear RNA quality control (ZC3H18, ZCCHC7, and PAPD5)." (PMID 26549460, 2015).
ZCCHC7 also shares sentences with these, for which no sentence is quoted: diffuse large B-cell lymphoma (1 paper); myeloma (1).